CHN1 (chimerin 1)
Diseases named in the same sentence as CHN1 in open-access papers (continued):
Sharing a sentence is not in itself a finding about the gene and the disease.
cancer (7 papers, 2013 to 2026). A tumor composed of atypical neoplastic, often pleomorphic cells that invade other tissues. "CHN1 expression was associated with immune infiltrates and this gene showed potential involvement in multiple cancer-related pathways." (PMID 34152250, 2021). "Moreover, bioinformatics prediction has shown that CHN1 is a putative target of miR-205 and a potential cancer-associated gene listed in the Cancer Gene Census." (PMID 33109127, 2020). "In our study, the majority of DEGs between LGGs are associated with normal neuronal development, like CHN1 and NEFL (NFL) are expressed in cerebral cortex and active in synaptic genesis and function, while in cancer those genes play as oncogenes." (PMID 40382536, 2025). "Since EMT is one of the key elements for cancer metastasis, the expression of CHN1 and one of the key EMT transcription factors, Snail, was detected in 24 serial-sliced CC samples to assess the correlation between these two proteins." (PMID 34238315, 2021). "In five pairs of CC and matched adjacent tissues, CHN1 was found highly expressed in tumors compared with that in the corresponding non-carcinoma tissues." (PMID 34238315, 2021). "IHC was further performed to confirm the expression status of CHN1 in 62 paired CC/adjacent non-carcinoma TMA, and three representative pairs are shown." (PMID 34238315, 2021). "Further, our co-expression analysis also showed that key EMT-related factors such as MMP2, MMP9, CDH2, TGFB1, and VIM were highly expressed when CHN1 was highly expressed, while CDH1 was expressed at lower levels, suggestive of a potential cancer-promoting function of CHN1." (PMID 34152250, 2021). "Our results show that high CHN1 levels could be used as a clinical biomarker for poor prognosis and that CHN1 inhibitors may have potential as anti-cancer drugs." (PMID 34152250, 2021). "However, CHN1 was mainly expressed in the basal cells of adjacent non-carcinoma epithelium tissues, due to rapid cell division and active cell proliferation." (PMID 34238315, 2021). "However, limited information on CHN1 has been reported in relation to cancer." (PMID 34238315, 2021). "Accordingly, we constructed a PPI network centered around CHN1 as the core gene and found an association between the expression of CHN1 and ERBB2, which is involved in the pathogenesis and adverse consequences of various cancers, including terminal GC and gastro-esophageal junction cancer." (PMID 34152250, 2021). "Among these samples, strongly positive expression of CHN1 was clearly observed in high-, medium-, and low-differentiation CC tissues, with an overall positive rate of 85.5% (53/62), which was notably different from the rate in non-carcinoma tissues (43.5%, 27/62)." (PMID 34238315, 2021). "In contrast, CBX3, CHN1, SULF1 and VDAC1 were significantly elevated in SKCM compared to HD samples, while EDIL3 and PALLD demonstrated significantly lower expression levels in the cancer samples." (PMID 41350567, 2025).
tumor (7 papers, 2020 to 2025). "Experiments on nude mice in vivo also supported the finding that higher levels of CHN1 promoted tumorigenesis, while lower levels inhibited tumor size." (PMID 34238315, 2021). "The effect of CHN1 overexpression and interference on xenograft tumor growth was determined by tumor weight and pathological analyses." (PMID 34238315, 2021). "Multivariate analysis revealed that CHN1 overexpression, age, and tumor stage were all closely corelated with poor prognosis in GC (P < 0.05)." (PMID 34152250, 2021). "Overexpression of CHN1 promoted tumor formation in an in vivo xenograft tumor mouse model, with increased tumor volumes and weights." (PMID 34238315, 2021). "The CIBERSORT algorithm was used to evaluate the correlation between CHN1 expression in the tumor microenvironment and tumor-infiltrating immune cells." (PMID 34152250, 2021). "CHN1 protein expression was abnormally increased in tumour cell masses/cords, but was barely detectable or undetectable in normal cervical epithelium and noncancerous cervical stratified epithelium." (PMID 33109127, 2020). "Therefore, the expression of CHN1 in tumor tissues was significantly higher than that in paracancerous tissue (P < 0.0001)." (PMID 34152250, 2021).
CHN1 also shares sentences with these, for which no sentence is quoted: breast cancer (2 papers); cognitive defects (2); Hypertension (2); neurodegenerative disease (2); alcohol dependence (1); asthma (1); atopic dermatitis (1); Bardet-Biedl syndrome (1); bipolar disorder (1); cervical tumours (1); congenital diaphragmatic hernia (1); dermatomyositis (1); diffuse large B-cell lymphoma (1); Down syndrome (1); Eczema (1); epilepsy (1); Epileptic encephalopathy (1); infection (1); lung carcinoma (1); lymphoma (1); migraine without aura (1); Moebius syndrome (1); Myocardial fibrosis (1); neurological diseases (1); Parkinson disease (1); schizophrenia (1); squamous cell carcinoma (1).